HLA-F (major histocompatibility complex, class I, F)
Diseases named in the same sentence as HLA-F in open-access papers (continued):
Sharing a sentence is not in itself a finding about the gene and the disease.
inflammation (1 paper, 2022). Aberrant reaction of the microcirculation characterized by movement of fluid and leukocytes from the blood into extravascular tissues. "Our data support that airway inflammation in an asthmatic context impacts HLA‐F mobilisation on HBEC and PLT surfaces independently of transcriptional level." (PMID 35988034, 2022).
HLA-F also shares sentences with these, for which no sentence is quoted: Autoimmunity (2 papers); brain glioma (2); ankylosing spondylitis (1); bronchiectasis (1); celiac disease (1); chorioamnionitis (1); colorectal cancer (1); cutaneous melanoma (1); dementia (1); diabetic nephropathy (1); Exotropia (1); germ cell tumor (1); germinoma (1); hemochromatosis (1); Hodgkins lymphoma (1); Hutchinson-Gilford progeria (1); infectious mononucleosis (1); lung adenocarcinoma (1); lung disease (1); malignant glioma (1); multiple sclerosis (1); neuroblastoma (1); parasite infection (1); polycystic ovary syndrome (1); psoriatic arthritis (1); renal cell carcinoma (1); rheumatologic disorders (1); sickle cell disease (1); thyroid cancer (1); viral myocarditis (1).